TNF (tumor necrosis factor)
Diseases named in the same sentence as TNF in open-access papers (continued):
Sharing a sentence is not in itself a finding about the gene and the disease.
pancreatitis (continued). "Previous studies have shown that diosmetin can ameliorate pancreatitis by inhibiting the generation of proinflammatory mediators such as interleukin (IL)-1β, IL-6, and tumor necrosis factor-α (TNF-α)." (PMID 31906574, 2020). "Pro-inflammatory cytokines, such as TNF-α, IL-6, and IL-1β, that are released during the course of pancreatitis mediate the pathogenesis of SIRS including lung injury." (PMID 29847178, 2018). "In pancreatitis, the inflammatory response is triggered by the production of a series of inflammatory cytokines such as IL-6, IL-1β, and TNF-α." (PMID 29849486, 2018). "In our current study, we found that pretreatment with ghrelin in rats with intact sensory nerves reduces the pancreatitis-induced increase in plasma concentration of TNF-α." (PMID 28665321, 2017). "TNFα reveals vital functions in the pathogenesis of inflammatory diseases, as inhibition of TNFα ameliorates the duration of experimental pancreatitis." (PMID 28587181, 2017). "Measurement of serum TNF-α concentration was suggested to be useful biomarker in predicting severe pancreatitis and development of multiorgan failure or septic shock." (PMID 28665321, 2017). "The peak expression of L-1β, IL-6, and TNF-α in the lung tissue occurred at 12 h after the induction of pancreatitis." (PMID 29359164, 2017). "Inhibition of p38 MAPK decreased injury to the lung through attenuated production of TNF-α and nitric oxide in the rat model of pancreatitis-induced ARDS." (PMID 28634422, 2017). "In experimentally induced pancreatitis, IL-10 levels parallel serum TNF levels and anti-IL-10 treatment reduce lung injury and pancreatic acinar necrosis, as well as reducing mortality from 42% to 0%." (PMID 28751922, 2017). "Pretreatment with GHRL in rats with intact sensory nerves reduced the pancreatitis-induced increase in plasma concentration of TNF-α." (PMID 29068376, 2017). "NF-κB is known to regulate the expression of inflammatory cytokines such as IL-1β, TNF-α, and IL-6, which induce the acute and edematous form of pancreatitis." (PMID 29068376, 2017). "In our study, the loss of JAM-C also resulted in significantly higher levels of serum TNF-α and IL-6 in experimental pancreatitis." (PMID 26841848, 2016). "There was a statistically significant difference between the Eugenol and Control groups 72 hours after induction of pancreatitis, while both groups exhibit higher TNF-α expression than the Sham group." (PMID 26884642, 2016). "Recent articles further supported that TNF-α antibody played an important protective role in pancreatitis in rats." (PMID 26249268, 2015). "TNF-α levels are elevated in the serum of patients with pancreatitis and in animal models of pancreatitis." (PMID 26095761, 2015). "IL-1 and TNF-α act both locally to aggravate the pancreatitis process and systemically, activating cytokines and leukocytes." (PMID 25265022, 2014). "The proinflammatory cytokines TNF-α and IL-1β are known to mediate amplification of inflammatory process during pancreatitis." (PMID 25214720, 2014). "Proinflammatory cytokines such as TNF-α and IL-6 are involved in the pathophysiological processes of pancreatitis." (PMID 24705157, 2013). "A pronounced TNF-α peak was present in at 24 h, while at 48 h after pancreatitis induction this expression returned to control values." (PMID 23110041, 2012). "In the present study, plasma levels of TNF-α, IL-1ß, IL-6, and IL-10 gradually increased after induction of pancreatitis, with peak levels occurred after 48 or 72 h." (PMID 23029434, 2012). "The production of pro-inflammatory cytokines, including IL-1, IL-6 and TNF-α, has now been shown in the majority of animal models of pancreatitis." (PMID 23181131, 2012). "In experimental pancreatitis, the plasma levels of TNF-α, IL-1ß, and IL-6 are elevated and their blockade attenuates the disease process." (PMID 23029434, 2012).
pancreatitis (continued). "In particular, KO mice have demonstrated that Ctsb plays a major role in pathological trypsinogen activation in the early course of experimental pancreatitis, and contributes to TNF-alpha induced hepatocyte apoptosis." (PMID 21897848, 2011). "TNFα expression in the pancreas is increased by the onset of experimental pancreatitis, and antagonism of TNFα reduces the severity of local pancreatic inflammation." (PMID 20396411, 2010). "Plasma levels of pro-inflammatory cytokines (TNF-α, IL-1β) in the pancreatitis group were significantly higher (p < 0.001) than that of the control group, while treatment of proanthocyanidin abolished these elevations significantly (p < 0.01)." (PMID 27956946, 2009). "It has been suggested that pro-inflammatory cytokines, such as TNF-α and IL-1β are upregulated during pancreatitis." (PMID 27956946, 2009). "It is increasingly appreciated that inflammatory mediators-such as interleukins, TNF-α, etc. -play a pivotal role in the development of clinical pancreatitis." (PMID 19636174, 2009). "The ability of TNF-α to regulate apoptosis in isolated pancreatic acini and experimental pancreatitis has previously been reported." (PMID 19356238, 2009). "The aim of this study wasto investigate the association between early changes (within 24 hours) in theserum IL-2, IL-4, TNFα, and IL-6 concentrations and occurence ofsubsequent pancreatitis complication after ERCP." (PMID 18670651, 2008). "We found that the levels of TNFα were increased at 12 hours after ERCP in thepatients with post-ERCP pancreatitis compared with those of the patientswithout pancreatitis." (PMID 18670651, 2008). "After administrating anti-TNFα therapy, we observed significant improvements in intestinal permeability and pancreatitis, indicating that it may be a potential therapeutic approach for improving intestinal permeability." (PMID 39856555, 2025). "Vice versa, previous studies could show that the secretion of CCL5 along with TNF-α by macrophages induced acinar-to-ductal metaplasia in pancreatitis, pointing to their role in early malignant transformation." (PMID 40282185, 2025). "Next, we conducted a study to isolate the effect of azathioprine and mercaptopurine (AZA/6MP), which is commonly prescribed together with TNF inhibitors, especially IFX and ADA, in combination therapies; it has been known for its association with drug-induced pancreatitis." (PMID 39712842, 2024). "Also, a study stated that TNF-α production was significantly increased in pancreatitis rats as compared with non pancreatitis control rats." (PMID 38333760, 2024). "Moreover, TNF-α levels, which were elevated in animals with pancreatitis, were significantly reduced in the treated animals." (PMID 39139157, 2024). "In line with these pro-stress effects, we demonstrated that prolonged cer-pancreatitis led to a significant reduction in acinar cells viability, accompanied by a gradual elevation in the expression of TNFα and IL-6 in response to pancreatitis-mimicking induction in vitro." (PMID 38927047, 2024). "An interesting aspect of the relationship between TNF inhibitors and pancreatitis is that in animal models, it has in fact been shown that TNF inhibitors may be an effective therapy for pancreatitis." (PMID 39712842, 2024). "These investigators suggested that IL-6 and TNF-α have a role in developing pancreatitis." (PMID 38533139, 2024). "However, pancreatitis or local pancreatic injury can induce the release of a plethora of inflammatory factors such as TNF-α and IL-1β, thereby triggering activation of the caspase-3 pathway and subsequent apoptosis of intestinal mucosal epithelial cells." (PMID 39450142, 2024). "TNF-α has also been researched as a possible pancreatitis treatment target." (PMID 39139157, 2024). "In addition, also pro-inflammatory mediators such as TNFα and IL-1β can activate pancreatic stellate cells, suggesting that fibrosis is initiated already during the acute phase of pancreatitis." (PMID 37881430, 2023).
pancreatitis (continued). "Studies in rats have demonstrated that acinar cells can respond to TNF- α and could mediate apoptosis, which would contribute to the development of pancreatitis and necrosis of the pancreatic tissue." (PMID 35041718, 2022). "Moreover, TNF-α was verified to play a core role in the pathogenesis of inflammatory diseases, particularly in pancreatitis pathogenesis." (PMID 35042436, 2022). "Twelve hours after the caerulein challenge, the pancreas injury index, including serum lipase, α-amylase and inflammatory cytokines, including IL-6 and TNF-α, were significantly upregulated in mice induced with caerulein pancreatitis but decreased significantly after JTE-013 intervention." (PMID 36229875, 2022). "The toxic effects of IFN-γ and TNF are thought to play a role in the pathogenesis of pancreatitis." (PMID 35925682, 2022). "Furthermore, PARP inhibitors have demonstrated effects on reducing pro-inflammatory mediators in the plasma such as TNF-α, IL-1β, IL-2, IL-4, IL-6, IL-12, IP-10, and KC on in vitro models of pancreatitis as well as in vivo models of wound healing injuries." (PMID 33663560, 2021). "The fact that pancreatitis is an inflammatory condition is supported by increases in parameters associated with inflammation, such as C-reactive protein (CRP), Interleukin 6 (IL-6) and Tumor necrosis factor α (TNF-α), as well as histologic findings." (PMID 34256804, 2021). "Pancreatitis is therefore likely mediated by the crosstalk of intrapancreatic protease activation and inflammation mediated by NF-κB activation within macrophages through pro-inflammatory cytokines, such as TNF (reviewed)." (PMID 34572737, 2021). "Therefore, the levels of IL-6, IL-1β, and TNF-α in LPS-induced pancreatitis model in vitro were detected." (PMID 33824873, 2021). "IL-6 levels which could be induced by TNFα and IL-1β, are elevated in pancreatitis and serve as markers of the severity of pancreatitis." (PMID 32587518, 2020). "For example, a Dutch study did define a genetic passport that included several loci (TPMT, NUDT15, HLA-DQA1*02:01-HLA-DRB1*07:01, and HLA-DQA1*05) associated with toxic effects from thiopurines (i.e., myelosuppression and pancreatitis) and anti-TNFα mABs (i.e., immunogenicity)." (PMID 33628180, 2020). "Intraperitoneal administration of LPS could increase the TNF-α production by peritoneal macrophages and hence mediate severe liver damage in pancreatitis rats, leading to development of multiple organ failure." (PMID 31827377, 2019). "For example, in male WBN/Kob rats, TNF-α and IL-6 concentrations peak well before the peak of disease severity what may suggest that both these proteins are involved in the onset of pancreatitis." (PMID 31624954, 2019). "In fact, TNF-α is known to be highly upregulated in pancreatitis with severe pancreatic fibrosis." (PMID 30923340, 2019). "Indeed, almost all risk factors for PDA, such as pancreatitis, are associated with chronic inflammation, and activation of NF-κB and TNF-α is crucial for the development of pancreatitis." (PMID 25846752, 2015). "In addition, the pancreatitis-induced increase in blood plasma TNFα levels were also greater in Ifnar1SA (7.89 fold) than in Ifnar1+/+ (4.50-fold) mice." (PMID 24480543, 2014). "Moreover, the levels of Th1 inflammatory mediators including IL-6, IL-1β, IFN-γ, and TNF-α decreased in pancreatic tissue after fucoidan intervention, indicating that fucoidan could relieve Th1 cells and Th1 cytokine-mediated pancreatitis locally." (PMID 38164477, 2024). "However, none of these works studied the risk of pancreatitis associated with TNF inhibitor use, which is a particularly important adverse effect as pointed out by a large number of case reports." (PMID 39712842, 2024).
pancreatitis (continued). "This could be evidenced in our experimental model of pancreatitis as well as in the previous study that reported an overexpression of TNF-α in both acinar and infiltrating cells after the induction of CP which was significantly correlated with the degree of fibrosis." (PMID 39424751, 2024). "The finding that CTZ and ETN had a negative association with pancreatitis may be partially explained by the fact that some TNF inhibitors, including ETN and CTZ, have shown to have protective function against pancreatitis." (PMID 39712842, 2024). "Serum concentrations of pro-inflammatory cytokines, such as tumor necrosis factor α, and interleukins, such as interleukin-1 beta (IL-1), interleukin-6 (IL-6), and interleukin-8 (IL-8), were significantly higher in severe pancreatitis compared with mild pancreatitis." (PMID 36979645, 2023). "Pancreatitis is therefore a distinctive form of inflammation, in which NF-κB plays a central role and may therefore be amenable to biologic therapies, such as inhibitors of cytokines or their receptors (e.g., anti-IL-6, IL-1Rα, anti-TNF)." (PMID 34572737, 2021). "Studies in patients and animals have identified the disease course and severity of pancreatitis is mostly governed by inflammatory cells that drive the upregulation of local and systemic immune responses, of which a major contributor is the inflammatory cytokine tumor necrosis factor (TNF)." (PMID 34049483, 2021). "Moreover, emodin could notably decrease the release of pancreatitis markers (amylase and lipase) and inflammatory mediators, such as TNF-α, IL-1β, and IL-6." (PMID 29163548, 2017). "Interestingly, states of acute inflammation such as pancreatitis and cardiac surgery demonstrate a similar monocyte anergy with reduced TNFα production, and ICs may inhibit in vitro-activated human monocytes by suppressing intracellular pathways via CD64." (PMID 26406605, 2015). "Both TNF-α and TNF-β (recently known as Lymphotoxin-α, LT-α) are inflammatory mediators belonging to the same family, TNF superfamily and become upregulated in pancreatitis." (PMID 38910880, 2024). "In the progression of pancreatitis in mice, LMT-28 treatment also reduced the expression of the proinflammatory cytokines IL-1β and TNF-α." (PMID 36643585, 2023). "Therefore, we surmise that TMAO causes the expression of the proinflammatory factors IL-1β, IL-6, and TNF-α to increase significantly by activating the p65 NF-κB pathway, which increases the level of Ca2+ in pancreatic acinar cells, inducing a sensitive state of pancreatitis." (PMID 34925503, 2021). "In order to further explore the relationship between the results of this experiment and human AP, we analyzed the expression of three key genes TNF, NOS3, and TGFB1 in human pancreatitis tissues." (PMID 34925503, 2021). "During pancreatitis, serum amylase, lipase and cytokine, such as IL6, IL-1β and TNF-α, levels are increased." (PMID 32842687, 2020). "In pancreatitis as can happen after IRE, various inflammatory mediators are released with concomitant thrombosis, resulting in high levels of IL-6, IL-8 and TNF." (PMID 31684186, 2019). "Among the upstream mediators activated in the Ptf1a cKO model are TNF-α and NFkB, both of which promote ADM and inflammation in pancreatitis and amplify KRAS activity in pancreatic tumorigenesis." (PMID 26151762, 2015). "In the present pancreatitis study, RAI with ATL significantly decreased the content of pro-inflammatory cytokines, such as TNF-α, IL-1β and IL-6." (PMID 25265022, 2014). "In our study, serum TNF-α and TNF-αmRNA expression in the pancreas was reduced after hydrogen-rich saline was administrated in the pancreatitis induced by taurocholate." (PMID 23983797, 2013). "Our results demonstrated that administration of diazepam (5 mg/kg i.p.)reduced amylase and lipase activity, TNF-alpha, MPO activity, and pathological alterations, which are markers of pancreatitis." (PMID 23956866, 2013).
pancreatitis (continued). "Biochemical and immunological assays confirmed that administration of EAE reduced amylase and lipase activity, TNF-alpha, IL-6, MPO activity, and lipid peroxidation which are markers of pancreatitis." (PMID 23008778, 2012). "On the other hand, pancreatic acini produce TNF-α and express TNF-αR1 in a model of pancreatitis suggesting a role of TNF-α in the autocrine regulation of apoptosis." (PMID 19356238, 2009). "In the first study, the levels of TNFα werereported to be significantly increased at 8 and 24 hours after ERCP in thepatients with post-ERCP pancreatitis." (PMID 18670651, 2008). "The enhancement of serum TNFα and IL-6 levels in the patients with ERCP-induced pancreatitis reflects the inflammatory activity." (PMID 18670651, 2008). "a denotes TNF inhibitor use and pancreatitis, b denotes TNF inhibitor use and no pancreatitis, c denotes other drug use and pancreatitis, d denotes other drug use and no pancreatitis." (PMID 39712842, 2024). "Irisin addition in the cer-pancreatitis state resulted in a significant down-regulation of the PPARγ-PGC1α-FNDC5 axis, PPARγ nucleus-translocation and inflammatory state (TNFα and IL-6) in parallel to diminished PL expression and secretion (in vitro and ex vivo models)." (PMID 38927047, 2024). "Although we did not investigate the specific role of IL11 in the immune response in pancreatitis, we found that blocking IL11 signalling had anti-inflammatory effects and reduced IL6, IL1β and TNFα protein levels as well as diminishing NF-κB and STAT3 activation." (PMID 35408908, 2022). "The KEGG analysis revealed that pathways in cancers, TNF signaling way, and MAPK signaling way might play an important role in pancreatitis therapy." (PMID 33824873, 2021). "Overall, these data suggest that during the process of pancreatitis-enhanced carcinogenesis by KrasG12D, EHMT2 influences immunomodulatory processes, while reducing EMT, TNF-α signaling via NFκB, and KRAS signaling, which have well-documented effects on growth promotion." (PMID 34249932, 2021). "It has previously been reported that SNS decreases TNF-α expression in trinitrobenzene sulfonic acid-induced pancreatitis, which does not seem to involve barrier restoration." (PMID 28854971, 2017). "3-AB attenuated the activation of adrenal NF-kB, TNF-α and ICAM-1 in pancreatitis." (PMID 27465581, 2016). "Silva hypothesized that the release of inflammatory mediators such as tumor necrosis factor (TNF)-alpha and interleukin (IL)-1 during an acute episode of pancreatitis may induce widespread vascular endothelial injury." (PMID 24386889, 2014). "Furthermore, QYT effectively decreased the levels of TNF-α, IL-6 and IL-8 in patients with pancreatitis, indicating that QYT functions by downregulating the expression of TNF-α." (PMID 25371738, 2014). "The administration of 90 μg/kg G-CSF 1 hour before the induction of pancreatitis in rats increased the number of peritoneal-exudate neutrophils and circulating neutrophils without increasing the concentration of TNF-α, IL-6, and IL-1β." (PMID 25551560, 2014). "In addition, the level of TNF-a and IL-6 in SAP rats increased and reached a peak at 3 h after pancreatitis was induced, then gradually decreased." (PMID 24312352, 2013). "In the patients without post-ERCP pancreatitis, thelevels of IL-4, TNFα, and IL-6 at 24 hours after ERCP were also higherthan those of the basal levels." (PMID 18670651, 2008). "In thepatients with post-ERCP pancreatitis and without pancreatitis, significantlyhigher levels of TNFα and IL-6 were found at 12 hours after ERCP comparedto the levels before ERCP." (PMID 18670651, 2008). "Moreover, “macrophage classical activation signaling pathway” and proinflammatory upstream signaling (tumor necrosis factor [TNF] and interleukin 1β [IL-1β]) had gradually increasing heat intensity patterns with pancreatitis disease progression along the continuum of AP, RAP, and CP." (PMID 39318759, 2024).